TSC1 (TSC complex subunit 1)
Diseases named in the same sentence as TSC1 in open-access papers (continued):
Sharing a sentence is not in itself a finding about the gene and the disease.
tumor (continued). "Thus, loss of genes encoding NF1, TSC1, or TβRII resulted in tumor cell-autonomous inflammatory reprogramming through the activation of the JAK-STAT3/6 pathway and resulted in increased production of IL6 and IDO1." (PMID 38997291, 2024). "Therefore, abnormal mTOR activation via loss of functional Tsc1 or Tsc2 promotes oncogenesis by maintaining the necessary cellular signals for tumor growth, survival, and proliferation." (PMID 39352796, 2024). "The TSC1 (9q34) and TSC2 (16p13.3) genes encode two tumor suppressor subunits, TSC1–Subunit 1 or Hamartin (1164 amino acids; 129,767 Da) and TSC2–Subunit 2 or Tuberin (1807 amino acids; 200,608 Da) of the TSC complex, which negatively regulates anabolic cell growth." (PMID 37509254, 2023). "On the contrary, TSC1, implicated as a tumor suppressor, is the target of miR-6728." (PMID 37686696, 2023). "The two tumor suppressor genes TSC1 and TSC2 are associated with the onset of TSC." (PMID 35692821, 2022). "Inactivating TSC1 mutations are associated with tumour formation due to mTORC1 overactivity." (PMID 35884550, 2022). "Of these, only TSC1 was strongly associated with tumor progression." (PMID 35677048, 2022). "Notably, Tsc1 interaction with Tsc2 was compromised in this model resulting in loss of Tsc2 tumor suppressive function." (PMID 35883484, 2022). "Rapalogs reduce tumor size by inhibiting the dysregulated activity of mTORC1 that results from biallelic inactivation of TSC1 or TSC2 and loss of activity of the encoded proteins, namely TSC1 (hamartin) or TSC2 (tuberin), which act as repressors of the metabolic activator kinase mTOR7." (PMID 34764250, 2021). "Specifically, in the case of loss of Tsc1/2 function, use of ER stress-inducing agents has displayed sensitization of mutant cells to individual treatments in vitro, or combination treatments in a mouse xenograft tumor model." (PMID 32525804, 2020). "TSC is a multisystem, autosomal dominant condition, which might present as a single, index case or familial disorder, caused by germline mutations in the TSC1 or TSC2 tumor suppressor genes, which encode for the hamartin and tuberin proteins, respectively." (PMID 32397669, 2020). "We posit that this is a general pattern of hereditary cancer predisposition, wherein haploinsufficiency for VHL or TSC1/2, or potentially other tumor susceptibility genes, is sufficient to promote development of early lesions, while cancer results from inactivation of the remaining normal allele." (PMID 27682873, 2017). "Tuberous sclerosis complex (TSC) is an autosomal dominant disorder characterized by the formation of benign tumors in multiple organs including kidney, brain, skin, and heart, which is caused by inactivating mutations in either of two tumor suppressor genes: TSC1 or TSC2." (PMID 28903387, 2017). "In addition, a malignant histiosarcoma patient had TSC1 missense mutation (p.A307V) and showed significant tumor reduction (−24.3%)." (PMID 26859683, 2016). "In addition, loss of Tsc1 in mouse subventricular zone neural stem/progenitor cells leads to migration deficits that result in the development of nodular protusions and small tumours that present many features of the brain lesions found in TSC patients." (PMID 26412398, 2015). "TSC1 mutation status is known for 148 tumours in the series, of which 14 contain a mutation." (PMID 24367658, 2013). "They then identified somatic Tsc1 mutation in ~80% of these tumours but only in one third of cysts." (PMID 23105973, 2012). "The HBx-associated IKKβ/TSC1/mTOR signaling pathway may play a molecular switch that allows HBV-related HCC tumor progression." (PMID 22848663, 2012).
tumor (continued). "We asked whether TSC2 repression was sufficient and required for ISC differentiation downstream of N, and found that loss of TSC1/2 indeed rescued the tumor phenotype of NRNAi expressing ISCs (in both MARCM clones, and when driven by esg::Gal4)." (PMID 23144631, 2012). "Furthermore, deletions of some mTOR pathway tumor suppressors such as tuberous sclerosis complex 1 and 2 (TSC1 and TSC2) and neurofibromatosis type 1 (NF1) are associated with both, benign and malignant mesenchymal tumors." (PMID 22701332, 2012). "GPNMB reactivity is non‐specific and cannot distinguish between FLCN‐mutated tumours and TFE3/TFEB RCCs, as well as various other TSC1/2/MTOR‐mutated tumours, but it may be diagnostically useful for screening for FLCN mutations that would help distinguish them from their mimics." (PMID 41384711, 2026). "Whereas wild-type TAMs display pro-inflammatory and pro-angiogenic transcriptional profiles, TSC1-deficient TAMs vacate perivascular niches, reduce Procr+ endothelial progenitor populations, and normalize vascular permeability, collectively inducing tumor hypoxia and cancer cell death." (PMID 41417432, 2025). "When the TSC1 gene is mutated or its function is impaired, it may lead to excessive activation of the mTOR signaling pathway, promoting cancer cell proliferation, metastasis, and tumor development." (PMID 38890443, 2024). "Their findings indicated that the tumor may demonstrate copy number amplification of chromosomes 16, 7, 13q, and 19p, as well as copy number deletion of Xp11.21 and 22q11.23, along with loss of heterozygosity of TSC1 and TSC2." (PMID 38892169, 2024). "Notably, depletion of CUL4B or MTA1 in CXXC5-overexpressing tumors led to a diminished effect of CXXC5 overexpression; consistently, the decrease in tumor growth associated with CXXC5 knockdown could be rescued by the simultaneous silencing of TSC1." (PMID 36539038, 2023). "TSC1 or TSC2 loss of function and subsequent mTORC1 activation, which drives tumor formation and vascular changes, have been investigated using rodent models, exploiting a spontaneous mutation in Tsc2 in the Eker rat, or using targeted disruption of Tsc1 or Tsc2 in mice." (PMID 28695825, 2017). "They further showed that LAG3 and PD-L1 targeting therapies inhibit metastasis in NF1-, TSC1-, or TGF-β RII-deficient tumours." (PMID 40650785, 2025). "In TSC1-knockdown groups, tumor cells exhibited significantly higher fluorescence intensity of proliferation marker KI67 compared to controls, while anti-PD-1 monotherapy and rapamycin treatment groups showed the lowest KI67 levels." (PMID 41445741, 2025). "This TSC1–mTORC1–sialylation axis provides a mechanistic explanation for how TSC1 influences the tumor immune microenvironment through glycosylation control." (PMID 41445741, 2025). "Our findings significantly expand the current understanding of TSC1’s biological functions beyond its canonical role as an mTORC1 inhibitor, revealing its novel capacity to modulate tumor immune evasion through glycosylation-dependent mechanisms." (PMID 41445741, 2025). "It is well-established that RHEB is a small GTPase that directly activates mTORC1 activity, but is negatively regulated by tumor suppressors TSC1/TSC2." (PMID 39762645, 2025). "TSC is caused by heterozygous pathogenic variants in either the TSC complex subunit 1 (TSC1) or the TSC complex subunit 2 (TSC2) tumor suppressor genes, which lead to overactivation of the rapamycin (mTOR) pathway and tumor formation in multiple organs." (PMID 40861726, 2025). "The Ezrin-radixin-moesin (ERM) domain of TSC1 (residues 881–1084) controls actin dynamics and cell adhesion, inhibiting tumor growth." (PMID 39901197, 2025).
tumor (continued). "AMPK phosphorylates tuberous sclerosis proteins 1 and 2 (TSC1/2), which act as tumor suppressors and regulate cell growth and division." (PMID 40983975, 2025). "To address this gap, we systematically investigated the biological and clinical significance of TSC1, focusing on its mechanistic role in shaping the tumor immune microenvironment through aberrant sialylation." (PMID 41445741, 2025). "Functional assays confirmed that TSC1 knockdown significantly enhanced tumor cell proliferation and migration." (PMID 41445741, 2025). "The contribution of cochaperones prefoldin, HOP, Aha1, p23, FNIP1/2 and Tsc1 as well as the chaperonin TRiC to tumor suppressor stability is also discussed." (PMID 39352796, 2024). "HCCs with high c-MYC activation displayed a markedly higher TSC1/2 mutation rate, suggesting the important role of TSC/mTORC1 during c-MYC tumor development." (PMID 39325536, 2024). "TSC is an autosomal dominant genetic disorder, and in 60% of cases, it is due to spontaneous mutation in TSC1 and TSC2 tumor suppressor genes." (PMID 39130912, 2024). "AKT1 then inhibits the tumour-suppressor TSC1/2 complex, releasing its inhibition on RHEB, thereby activating mTORC1." (PMID 39568072, 2024). "Transwell, CCK-8 and tube formation assays demonstrated that depletion of TSC1 attenuated the effect of RNF26 overexpression on increasing tumor cell migration, proliferation, and angiogenesis." (PMID 38890443, 2024). "To evaluate the potential effect of PTEN/TSC1/TSC2 mutations and integrate the results with the differentiation state of tumor cells, we performed IHC analyses for mTORC1 activation (phospho-S6 Ser240/244)." (PMID 38775158, 2024). "Almost half of HCC patients show the presence of aberrant PI3K-AKT-mTOR signaling, including loss of the tumor suppressors PTEN, TSC1, and TSC23." (PMID 38696452, 2024). "Intratumor TAMs located in the tumor parenchyma adopt an mTORC1-low state dependent on tuberous sclerosis complex 1 (TSC1), a negative regulator of mTORC1 signaling." (PMID 39516356, 2024). "The tumor suppressor TSC (TSC1/TSC2) integrates GF and stress-sensing signaling pathways including the PI3K/AKT, LKB1/AMPK, Wnt/GSK3, and ERK/RSK pathways, to regulate the interaction between RheB and mTORC1." (PMID 38824577, 2024). "Currently, one key feature of TSC1/TSC2 biology is well understood: the ability of the TSC1/2 tumour suppressor complex to inhibit growth signalling through mechanistic target of rapamycin complex 1 (mTORC1)." (PMID 39070657, 2024). "Together, these data highlight the importance of conventional tumor suppressor genes (e.g., Tsc1 and Tgfbr2) in repressing tumor metastasis and the dynamic nature of clonal persistence and expansion." (PMID 38997291, 2024). "Perivascular TSC1-deficient TAMs outcompeted PROCR-expressing endothelial cells and suppressed neoangiogenesis, causing tumor tissue hypoxia and starvation-induced cancer cell death." (PMID 39516356, 2024). "Pathogenic variants in TSC1 or TSC2 lead to dysregulated cell growth, tumor formation, and tumor progression." (PMID 39902087, 2024). "The underlying pathophysiology of TSC revolves around mutations in the TSC1 or TSC2 genes, leading to the dysregulation of the mTORC1 pathway and resulting in abnormal cell proliferation and tumour growth." (PMID 39518472, 2024). "The primary function of Tsc1/2 as a tumor suppressor is to inhibit cell growth and proliferation by antagonizing the mammalian target of rapamycin (mTOR) pathway, a signaling network that is a regulatory hub for cell growth." (PMID 39352796, 2024). "A total of 869 downstream genes directly bound by the CXXC5–CRL4B–NuRD complex were identified, including TSC1, which is well recognized for its role in the regulation of mTOR signaling and tumor suppression." (PMID 36539038, 2023). "TSC manifestations are caused by mutations in either TSC1 (on chromosome 9q34) or the TSC2 gene (on chromosome 16p13.3), both recognized as tumor suppressors." (PMID 36769603, 2023).
tumor (continued). "Together, the data reveal miR-130b as a pro-oncogenic miRNA in LMS and support a miR-130b-TSC1 regulatory network that enhances tumor progression via inhibition of SM differentiation." (PMID 36701370, 2023). "All 3 BLCA PDX models with TSC1/TSC2 deficiency were sensitive to RMC-5552, which caused significant tumor volume reduction in 2 of 3 PDX models, and delayed tumor growth in the third." (PMID 37909334, 2023). "Collectively, these experiments indicate that the CXXC5–CRL4B–NuRD (MTA1) complex has a significant effect on promoting tumor growth, and that it does so by repressing target genes, including TSC1." (PMID 36539038, 2023). "Our data support a role for miR-130b in promoting the aggressiveness of LMS, in part by repressing TSC1, a tumor suppressor that controls anabolic cell growth and differentiation through inhibition of mammalian target of rapamycin (mTOR)." (PMID 36701370, 2023). "Somatic tumor analysis additionally demonstrated a TSC1 c.1525C>T (p.Arg509Ter) nonsense variant and LOH of 9q, resulting in a reduction to homozygosity of the TSC1 p.Arg509Ter variant." (PMID 36980535, 2023). "Tuberin forms a heterodimer with the protein product of TSC1, hamartin, which functions as a tumor suppressor by inhibiting the mTOR signaling pathway." (PMID 37041531, 2023). "Increased mTOR signaling is particularly related to human malignancies defined by the loss or mutation of critical tumor suppressors including STK11, TSC1/2, and PTEN which seem to be important for regulating the PI3K/Akt pathway." (PMID 36109789, 2022). "Then, we investigated the mechanisms of increased tumor-infiltrating CD8+ T cells in TSC1/TSC2-mutant tumors." (PMID 35119931, 2022). "An exponential graph of resolution of tumours over time revealed an average CR resolution age of 6.8 years old, with an average resolution age of 6.7 years old in TSC1 patients, and 7.2 years old in TSC2 patients." (PMID 35440050, 2022). "Overactivation and dysregulation of the mTOR pathway, which are caused by TSC1 or TSC2 abnormalities, promote tumor formation." (PMID 35359647, 2022). "TSC-related abnormalities such as tumour prevalence, location and size were analysed for each organ in addition to neuropsychiatric involvement and were compared between TSC1 and TSC2 mutant genotypes." (PMID 35440050, 2022). "TSC2 in complex with TSC1 has tumor suppressor functions via regulation of the mechanistic target of rapamycin kinase (mTOR) signaling pathway." (PMID 35962345, 2022). "Tumors in TSC have been suggested to be caused by the inactivation of both alleles of either TSC1 or TSC2 genes, consistent with Knudson’s two-hit tumor suppressor gene model." (PMID 35145067, 2022). "Overall, most patients with multiple CR had either two or three tumours, representing 43% and 65% of the patients in TSC1 and TSC2 cohorts, respectively." (PMID 35440050, 2022). "Previous genetic studies have shown that renal AML occurring in TSC cases was caused by the inactivation of both pairs of alleles of either TSC1 or TSC2, which is consistent with Knudson’s 2-hit tumor suppressor gene model." (PMID 35145067, 2022). "Li-TSC1−/− mice and Li-RagAGTP/Δ largely shared metabolic alterations, but Li-RagAGTP/Δ mice did not suffer the overt, aberrant hepatocellular damage and spontaneous tumor development seen in Li-TSC1−/− mice." (PMID 34135321, 2021). "Loss of function mutations in TSC1 and TSC2 genes results in constitutive mTOR activation and tumor progression." (PMID 35250965, 2021). "Recently, one tumor with confirmed monosomy 8 and ELOC deletion as well as a TSC1 mutation was documented." (PMID 34885018, 2021).
tumor (continued). "NetICS provides a comprehensive framework that reveals how specific genetic aberrations (i.e., deletion of the tumor suppressors Pten and Tsc1) and tumor-specific changes in miRNA expression can affect downstream mediators." (PMID 34348664, 2021). "TSC1 contributes to both tumor-suppressive and pro-metastatic action of the TGF-β-Smad pathway and works independently of TSC2, which is essential for cellular growth arrest and epithelial to mesenchymal transition." (PMID 34229737, 2021). "The TSC1/TSC2 complex is the main upstream regulator of mTOR, and hyperactivated mTOR, caused by the loss of TSC1 or TSC2, leads to uncontrolled cell proliferation and tumor growth." (PMID 34341336, 2021). "A tumor-agnostic registrational trial in cancers with TSC1 or TSC2 inactivating alterations is expected." (PMID 34442003, 2021). "Several deletion and knockout studies of TSC1 have established its tumor suppressive role in various cancers." (PMID 33833339, 2021). "The TSC1-TSC2 complex, a tumor suppressor, forms when TSC1 and TSC2 bind via their coiled-coil domains to form an intracellular complex, which helps switch the protein Ras homolog enriched in brain (Rheb) from its active state, Rheb-GTP, to its inactive state." (PMID 34445268, 2021). "In its GTP-loaded state, Rheb activates mTORC1, and this Rheb function is negatively regulated by the GTPase-activating protein (GAP) activity of the tumor-suppressing TSC complex composed of TSC1, TSC2, and TBC1D7." (PMID 33534698, 2021). "TSC1 plays a crucial role in facilitating multiple cellular functions including cell proliferation, adhesion and migration, autophagy, angiogenesis and tumor development." (PMID 33833339, 2021). "IL-1β and TNF-α, in particular, show a notable overlap of biological activity in cancer and promote tumor angiogenesis by inducing tumor cells to secrete VEGF via the IκB/TSC1/mTOR pathway." (PMID 33925400, 2021). "The overactivation of PI3k/Akt/mTOR pathway promotes glycolysis and glucose-dependence, leading TSC1/TSC2 mutant tumor cells entering apoptosis after glucose withdraw." (PMID 33821877, 2021). "We generated an mTOR-driven HCC mouse model, by liver-specific deletion of the tumor suppressors Pten and Tsc1, to investigate the molecular and cellular mechanisms of mTOR-driven tumorgenicity." (PMID 34348664, 2021). "TSC1 is a tumor suppressor that inhibits cell growth via negative regulation of the mammalian target of rapamycin complex (mTORC1)." (PMID 32927859, 2020). "The tumor suppressors, TSC1 and TSC2, function in both Drosophila and mammals as negative regulators of Rheb." (PMID 33329069, 2020). "Tuberous sclerosis complex (TSC) caused as a result of mutations in any of the two tumor suppressor genes, TSC1 and TSC2, leads to formation of localized tumor masses in multiple organs." (PMID 32742252, 2020). "For F5 that exhibited histologic centrifugal invasion, the pontine population showed a TSC1 pathogenic mutation at subclonal VAF, and this mutant subpopulation was selected and subsequently migrated to all other tumor areas." (PMID 32680567, 2020). "Intriguingly, while the loss of 1 or both alleles of Tsc1 increased SA β-gal levels, significant p16 staining was observed only in heterozygous mice, suggesting that upregulation of this tumor suppressor was inhibited in response to homozygous Tsc1 deletion." (PMID 32927859, 2020). "Decreased expression of STAT3 and a concomitant downregulation of p-STAT3 were observed in tumor tissues derived from miR-125b-5p-overexpressing Tsc1-/- MEFs compared to the corresponding control cells." (PMID 31949495, 2020).